FRMD4A (FERM domain containing 4A)
Description:
Scaffolding protein that regulates epithelial cell polarity by connecting ARF6 activation with the PAR3 complex (By similarity). Plays a redundant role with FRMD4B in epithelial polarization (By similarity). May regulate MAPT secretion by activating ARF6-signaling.
Synonyms: FRMD4; KIAA1294; FLJ10210; bA295P9.4; CCAFCA
Tractability: PROTAC: its protein half-life has been measured.
Gene: Protein-coding gene on chromosome 10 (13,643,706 to 14,462,142, reverse strand). Ensembl gene ENSG00000151474.
Subcellular location: Cytoplasm, cytoskeleton; Cell junction, adherens junction; Cell junction, tight junction
Subcellular location (Human Protein Atlas): Golgi apparatus; Nucleoplasm
Gene Ontology:
Molecular function: protein-macromolecule adaptor activity
Biological process: positive regulation of protein secretion; establishment of epithelial cell polarity; negative regulation of protein secretion
Cellular component: cytoplasm; adherens junction; bicellular tight junction; cytoskeleton
Genetic constraint (gnomAD): Loss-of-function variants: 16 observed, 53.33 expected, observed/expected ratio (o/e) 0.3, 90% interval 0.2 to 0.46. The synonymous counts are far from expectation, so gnomAD's model fits this gene poorly and the ratio says little. Missense variants: 992 observed, 901.7 expected, observed/expected ratio (o/e) 1.1, 90% interval 1.04 to 1.16. Synonymous variants: 484 observed, 401.45 expected, observed/expected ratio (o/e) 1.21, 90% interval 1.12 to 1.3.
Homologues: Orthologues: chimpanzee FRMD4A (97% identical), macaque FRMD4A (96% identical), mouse Frmd4a (95% identical), rat Frmd4a (95% identical), dog FRMD4A (94% identical), pig FRMD4A (94% identical), guinea pig FRMD4A (94% identical), rabbit FRMD4A (90% identical), tropical clawed frog frmd4a (87% identical), zebrafish frmd4a (79% identical), Caenorhabditis elegans F07C6.4 (20% identical). Paralogues in human: FRMD4B (47% identical), MSN (14% identical), RDX (14% identical), EZR (14% identical), NF2 (13% identical), ERMN (4% identical).
Diseases named in the same sentence as FRMD4A in open-access papers:
FRMD4A is named in the same sentence as 34 diseases in open-access papers, as found by Europe PMC text mining. Sharing a sentence is not in itself a finding about the gene and the disease. The quoted sentences say what the papers report.
nicotine dependence (6 papers, 2014 to 2025). Physical and psychological dependence on nicotine. "Interestingly, single nucleotide polymorphisms in FRMD4A have been shown to be involved in nicotine dependence." (PMID 25862628, 2015). "Since mutations in FRMD4A gene locus associate with nicotine dependence, prenatal smoking-induced DNA methylation of FRMD4A that persists until childhood might be an additional mechanism contributing to increased nicotine dependency of offspring exposed to in utero tobacco smoke." (PMID 27171005, 2016). "Of particular interest were findings in FRMD4A, ATP9A, GALNT2, and MEG3—genes that are implicated in processes related to nicotine dependence, smoking cessation, and placental and embryonic development." (PMID 24906187, 2014). "Thus, if the altered methylation states of FRMD4A and/or ATP9A persisted through adolescence, these could potentially contribute to the observed relationship between maternal smoking and smoking-related traits, such as nicotine dependence, in offspring." (PMID 24906187, 2014).
Alzheimer disease (4 papers, 2024 to 2025). A progressive, neurodegenerative disease characterized by loss of function and death of nerve cells in several areas of the brain leading to loss of cognitive function such as memory and language. "In Alzheimer’s disease, the gene encoding FRMD4A primarily functions as a risk factor." (PMID 41155374, 2025). "Notably, Frmd4a has been linked to an increased risk of developing Alzheimer’s disease." (PMID 41155374, 2025). "Markunas and colleagues showed that DNA methylation is changed in 110 gene regions and notably FRMD4A, a gene associated with Alzheimer disease (AD) and nicotine dependence and CNTNAP2, a gene associates with neural development, autism spectrum disorder, schizophrenia, and language impairment." (PMID 40115268, 2025). "Interestingly, integrated whole-transcriptome and genomic methylation analyses have identified both Frmd4a and Frmd4b as candidate gene products involved in networks specific to late-onset Alzheimer’s disease." (PMID 41155374, 2025).
Intellectual disability (3 papers, 2020 to 2025). "In contrast, in monogenic diseases such as certain forms of intellectual disability with global developmental delay, pathogenic variants in the gene encoding FRMD4A can be directly causative." (PMID 41155374, 2025). "It is also likely that heterozygous Frmd4a mutations are responsible for causing intellectual disability and ataxia with global developmental delay." (PMID 41155374, 2025). "Cell cluster-specific Gatad2b dosage-sensitive genes include Frmd4a, associated with intellectual disability and Robo1 that mediates proliferation and neurogenesis in development and is clinically associated with a neurodevelopmental disorder in cluster 0 (Layer II-VI)." (PMID 38238293, 2024). "Moreover, a homozygous mutation in FRMD4A has been linked to a syndrome of congenital microcephaly and intellectual disability." (PMID 33218114, 2020).
microcephaly (2 papers, 2017 to 2020). A congenital or acquired developmental disorder in which the circumference of the head is smaller than normal for the person's age and sex. "Genetic disruption of FRMD4A causes a syndrome characterized by congenital microcephaly accompanied by agenesis of corpus callosum and/or partial hypoplasia of the vermis and cerebellum and ID (MIM 616819)." (PMID 28713243, 2017). "FRMD4A regulates cell polarity in non-neuronal cells and the microcephaly and brain malformations reported in carriers of FRMD4A mutations are compatible with defects in cell polarity in neuronal progenitors and/or newborn neurons." (PMID 28713243, 2017).
Obesity (2 papers, 2019 to 2023). Accumulation of substantial excess body fat. "While gene PI16, DPY6, FRMD4A and CROCC have not been reported to be associated with nephropathy, they have been identified in T2DM and obesity-related traits." (PMID 37033211, 2023).
cognitive decline (1 paper, 2020). "FRMD4A (FERM domain-containing protein 4A) is a scaffolding protein that regulates epithelial polarity and has been previously identified as a genetic risk factor for LOAD and cognitive decline." (PMID 33218114, 2020).
diabetic nephropathy (1 paper, 2023). "The genes that contributed to the biological relevance of diabetic nephropathy, include gene TTN (rs72646845), PI16 (rs113848006), DPY6 (rs36027551), CROCC (rs41272737), PPP1R3A (rs1799999), ZNF136 (rs140861589), HSPA12B (rs6076550), and FRMD4A (rs1541010)." (PMID 37033211, 2023).
head and neck squamous cell carcinoma (1 paper, 2020). A squamous cell carcinoma that arises from any of the following anatomic sites: lip and oral cavity, nasal cavity, paranasal sinuses, pharynx, larynx, and salivary glands. "The up-regulation of FRMD4A was reported in human head and neck squamous cell carcinoma (HNSCC) and correlated with increased risks of relapse." (PMID 33035235, 2020).
Hydrocephalus (1 paper, 2024). Hydrocephalus is an active distension of the ventricular system of the brain resulting from inadequate passage of CSF from its point of production within the cerebral ventricles to its point of absorption into the systemic circulation. "Reduced Frmd4a in ependymal cells was linked to hydrocephalus and neurodegeneration." (PMID 39867878, 2024).
lung carcinoma (1 paper, 2024). "Association between gene-level methylation scores (AHRR*, MYO1G, CYP1A1, FRMD4A, and GFI1*) and lung cancer risk, among ever smokers (186 matched pairs) nested in the CLUE II cohort (1989–2018)." (PMID 39544416, 2024).
squamous cell carcinoma (1 paper, 2022). A carcinoma arising from squamous epithelial cells. "High expression of FRMD4A is associated with an increased risk of HNSCC recurrence, and the silencing of FRMD4A inhibits the growth and metastasis of human squamous cell carcinoma in skin and tongue metastases and reduces the proliferation and cell adhesion of squamous cell carcinoma." (PMID 35449571, 2022).
substance dependence (1 paper, 2014). The psychological or physiological need to take a substance in order to experience its effects or to avoid the effects of its absence. "We identified altered methylation of CpGs near two genes, FRMD4A and ATP9A, associated with nicotine and substance dependence, and the ability to quit smoking." (PMID 24906187, 2014).
cancer (6 papers, 2015 to 2023). A tumor composed of atypical neoplastic, often pleomorphic cells that invade other tissues. "Data mining of databases of HNSCC and other cancers reveals that high FRMD4A expression levels predict poor prognosis." (PMID 31060263, 2019). "The two mechanisms defined are intrinsically related to the pathogenesis of IBD, and likely will apply as general rules for the CUPID domains of FRMD4A, FRMD4B, and CCDC120 - proteins implicated in neurite outgrowth, and in human cancer, Alzheimer’s, celiac, and heart disease." (PMID 30355448, 2018). "Mechanistically, the protein product of FRMD4A is an Ezrin Radixin Moesin (ERM) protein, and like other ERM family members, reducing expression of FRMD4A appears to modulate the Hippo pathway, which has been implicated in the control of tissue growth and cancer development." (PMID 31060263, 2019). "For group 1, seven of the thirteen novel-loci-related coding or noncoding genes, namely F11/F11-AS1, PFKFB3, PRMT8, FAM66C, NAV2/NAV2-AS1, FRMD4A, and KIAA0232, have been demonstrated to be correlated with the development of HCC or other cancers in many studies." (PMID 38003606, 2023). "We observed the overexpression of isoforms of genes C3orf17, FRMD4A, FZD6, HNRNPA2B1, POSTN, PRKAA1, RRBP1 and VEGFA, and the under expression of TRIP12 isoform (ENST00000428959) in ACC patients who are not free of cancer, which is a surrogate for poor ACC outcomes." (PMID 33035235, 2020).
kidney disease (2 papers, 2023 to 2025). "Overall, NCOR2 and FRMD4A were consistently reported to be associated with kidney disease when referenced against the GWAS and EWAS catalogs." (PMID 39448372, 2025).
neurological disorders (2 papers, 2024 to 2025). "Frmd4a is associated not only with CCAFCA but also with several other neurological disorders." (PMID 41155374, 2025).
brain diseases (1 paper, 2025). "In both contexts, variations in Frmd4a exhibit a strong correlation with certain brain diseases." (PMID 41155374, 2025).
neurodegenerative disease (1 paper, 2025). A disorder of the central nervous system characterized by gradual and progressive loss of neural tissue and neurologic function. "Moreover, understanding how loss-of-function in Frmd4a or Frmd4b contributes to related neurodegenerative diseases, potentially due to disrupted neuronal tissue homeostasis, is of significant importance." (PMID 41155374, 2025).
FRMD4A also shares sentences with these, for which no sentence is quoted: Ataxia (2 papers); asthma (1); bipolar disorder (1); breast carcinoma (1); diabetes (1); entropion (1); glioma (1); heart disease (1); hereditary spastic paraplegia (1); Kohlschutter-Tonz syndrome (1); myxoma (1); Nephropathy (1); neurodevelopmental disorder (1); non-small cell lung carcinoma (1); Parkinson disease (1); schizophrenia (1); tumor (1).